TLDC2 (TBC/LysM-associated domain containing 2)
Description:
Inhibits the activity of the vacuolar-type ATPase (V-ATPase) by inducing disassembly of the V-ATPase complex. Protects neuronal cells against oxidative stress (By similarity). Required for kidney bicarbonate secretion (By similarity).
Synonyms: dJ132F21.2; C20orf118
Tractability: No criterion of Open Targets' tractability assessment is met for any kind of drug.
Safety:
Unwanted effects reported when the protein is acted on. In parentheses: how it was acted on, where the effect was seen, and who reports it.
sensory neuropathy (source: ClinPGx)
Gene: Protein-coding gene on chromosome 20 (36,873,061 to 36,894,237, forward strand). Ensembl gene ENSG00000101342.
Gene Ontology:
Biological process: response to oxidative stress
Cellular component: nucleus
Genetic constraint (gnomAD): Loss-of-function variants: 23 observed, 29.55 expected, observed/expected ratio (o/e) 0.78, 90% interval 0.56 to 1.1. The upper end of that interval is the gene's LOEUF score, 1.1, which puts it in group 4 of 6, group 1 being the genes least tolerant of losing a copy. Missense variants: 286 observed, 287.29 expected, observed/expected ratio (o/e) 1, 90% interval 0.9 to 1.1. Synonymous variants: 124 observed, 112.52 expected, observed/expected ratio (o/e) 1.1, 90% interval 0.95 to 1.28.
Homologues: Orthologues: chimpanzee TLDC2 (100% identical), macaque TLDC2 (96% identical), dog TLDC2 (84% identical), mouse Tldc2 (84% identical), rat Tldc2 (82% identical), pig TLDC2 (81% identical), rabbit TLDC2 (80% identical), guinea pig TLDC2 (79% identical), tropical clawed frog tldc2 (47% identical), Drosophila melanogaster mtd (42% identical), Caenorhabditis elegans lmd-3 (37% identical). Paralogues in human: OXR1 (47% identical), NCOA7 (44% identical), MEAK7 (26% identical).